C3 (complement C3)
Diseases named in the same sentence as C3 in open-access papers (continued):
Sharing a sentence is not in itself a finding about the gene and the disease.
renal disease (continued). "In juvenile SLE patients, both urine monocyte chemoattractant protein-1 (uMCP1) and serum C3 can indicate renal involvement, while both uMCP1 and uNGAL can predict subsequent renal disease activity changes." (PMID 37516706, 2024). "looked specifically at Gd-IgA1 and found a linear relationship between the serum Gd-IgA1/C3 ratio and kidney disease progression." (PMID 39188719, 2024). "Multivariable logistic regression models of active renal disease were constructed with age, gender, ethnicity, low C3 and/or C4 complement and high anti-dsDNA as covariates." (PMID 37516862, 2023). "The smaller fragment of C3, known as C3a, has been proved to play a vital role in the pathogenesis of several kidney diseases by binding to its receptor (C3aR)." (PMID 38082306, 2023). "Cfh−/− mice (6/26) succumbed to suspected renal disease by 8 months of age, with florid C3 and C9 deposition in the glomeruli of the mice, with some evidence of IgG deposits." (PMID 36203396, 2023). "Some factors were reported to be positively associated with kidney disease in pSS, including ANA, anti-SSA, anti-SSB, RF, low C3/C4, urea, creatinine, cystatin C, β2-microglobulin, etc.." (PMID 37735697, 2023). "Complement deposition in the kidneys identifies patients with more aggressive renal disease; patients with active disease display low serum levels of C3 and C4." (PMID 35242041, 2022). "Other laboratory indicators of active disease or renal disease, including C3, C4, and urine protein/creatinine ratio, were reviewed/examined at the time of B cell IFNβ analysis." (PMID 35436902, 2022). "Motivated by the demonstration of the increasing importance of C3 in renal disease we have generated a monoclonal antibody recognizing a conformational structure of the anterior part of the C3a/C3 molecule." (PMID 34767613, 2021). "In two studies, levels of C3 were found to be reduced more commonly in patients with renal disease than in the other group." (PMID 33042142, 2020). "Nevertheless, the anti-FH autoantibodies appear to have some functional consequences with respect to progression of renal disease in patients with C3G, perhaps in concert with other antibodies such as C3 nephritic factor." (PMID 31270173, 2019). "Serum and renal complement C3 levels were found to increase in diabetic patients with kidney disease." (PMID 31338070, 2019). "Patients with low levels of serum C3 are thought to have active renal disease, and the serum C3 level represents the severity of the disease; however, most patients were positive for complement C3 deposition in the kidney." (PMID 30453994, 2018). "Complement 3 is synthesised by glomerular cells, and tubular cells and the local synthesised C3 has been demonstrated to play a role in the development of kidney disease." (PMID 29692933, 2018). "In fact, inhibition of C3/C5 activation complex in MRL/lpr mice led to a reduction in renal disease and a significant decrease in thrombus size compared to controls." (PMID 30210500, 2018). "C3 glomerular disease (C3GN) refers to a group of recently identified rare renal disorders characterized by the presence of C3 in the absence or in the presence of limited deposition of immunoglobulins in the renal tissue." (PMID 28748184, 2017). "Another indicator of SLE is kidney disease triggered by IgG and C3 deposition within glomeruli, which can be assessed by proteinuria levels." (PMID 27149280, 2016). "Given the higher severity of renal disease in the low C3 group, we next analysed the relationship between C3 level and renal histologic lesions." (PMID 27391243, 2016). "Of note, anti-C1q antibodies displayed a closer association with renal disease activity in SLE patients than anti-dsDNA antibodies and reduction of C3 and C4 in terms of diagnostic specificity." (PMID 26549923, 2015).
renal disease (continued). "Our results suggest that serum anti-C1q antibody is more strongly associated with renal disease activity in SLE patients than anti-dsDNA antibodies and reduction of C3 and C4 in terms of diagnostic specificity." (PMID 26549923, 2015). "In complete FH deficiency, uncontrolled C3 activation through the alternative pathway results in plasma C3 depletion and complement-mediated renal disease." (PMID 24279761, 2014). "Experimental FH deficiency in pigs and mice results in uncontrolled AP activation characterized by low plasma C3 levels and renal disease due to abnormal accumulation of C3 within the glomeruli." (PMID 24279761, 2014). "C3 complement levels increased from 0.55 (0.05 to 0.79 g/l) during active LN to 0.90 (0.74 to 1.41 g/l, P = 0.0005) during quiescent renal disease." (PMID 23445537, 2013). "Compared with the previous study, this study had more parameters, including fibrinogen, D-dimer, serum IgA, and complement C3, all of which are known biomarkers of kidney diseases." (PMID 22738421, 2012). "Anti-HSP90 antibodies were present in 30–50% of the patients with SLE and those patients were more likely to have renal disease and a low C3 level." (PMID 23091704, 2012). "The presence of high concentration of hsp90 autoantibodies was found to correlate with renal disease and low C3 levels." (PMID 23091704, 2012). "Intercrossing Cfh−/− mice with mice deficient in factor B prevented the development of DDD demonstrating that the spontaneous renal disease was dependent on C3 activation through the AP." (PMID 19411110, 2009). "Until recently, standard approaches to treatment included supportive measures common to many kidney diseases and immunosuppression to mitigate inflammation, rather than specific therapies addressing the underlying C3 dysregulation." (PMID 41541782, 2026). "Several C3- and CFB-derived peptides were also associated with specific kidney disease etiologies." (PMID 41752115, 2026). "Specifically, overactivation of the complement cascade leads to the deposition and accumulation of C3 breakdown products along the glomerular basement membrane and within the mesangium, triggering glomerular injury and contributing to progressive kidney disease." (PMID 41541782, 2026). "Interestingly, C3 has been reported as a protein involved in a variety of kidney diseases, including AKI." (PMID 37627907, 2023). "Measuring systemic levels of C components and C activation products, in addition to studying C3, C4 and CH50, may be useful to predict diagnosis, disease activity and/or prognosis for C-associated diseases, including some kidney diseases." (PMID 36732701, 2023). "There are different components of the complement system in the kidney, especially C3 and C3 convertase in the proximal tubular epithelial cells attached to the membrane, which could activate intrarenal complement in diverse renal diseases." (PMID 35955802, 2022). "Our study has demonstrated that a reduction of C3 is related to kidney disease in patients with LN." (PMID 36451131, 2022). "Furthermore, fucose plays an important role in immunoregulation of renal disease by reducing the deposition of complement C3 on renal tubules and infiltration of immune cells, which is beneficial to the therapeutic intervention of IgAN." (PMID 36059518, 2022). "Within the subcohort of individuals with active renal disease, significantly more patients were anti-dsDNA antibody positive (p<0.001) and/or had pathologically low serum complement C3 and/or C4 levels (p<0.01) when compared with patients with inactive or no renal disease." (PMID 32723832, 2020). "Association between low C3 levels and C3 IF in AAV and renal disease and outcome." (PMID 32787590, 2020). "C3 activation is considered to contribute to several renal diseases." (PMID 30791918, 2019). "Glomerular C3 deposition has been studied in several kidney diseases." (PMID 30003098, 2018).
renal disease (continued). "Taken together, these data suggest C3-C3aR signaling promotes RF, and C3aR may be a therapeutic target for renal disease." (PMID 30405606, 2018). "SDR significantly enhanced kidney disease when compared to age-matched, randomly selected control counterparts, as measured by histopathological analysis of H&E staining and immunohistochemistry for complement component 3 (C3) and IgG complex deposition." (PMID 28491039, 2017). "Also, we did not perform the additional staining for complementary components in glomeruli, which were previously suggested to be putative predictors of disease activity as alternatives to C3 in the other kidney diseases." (PMID 28642464, 2017). "Moreover, anti-C1q antibodies showed a stronger association with renal disease activity in SLE patients than anti-dsDNA antibodies and reduction of C3 and C4 in terms of diagnostic specificity." (PMID 26549923, 2015). "Furthermore, we also observed significantly altered levels of complement C3 (p<0.001) and C4 (p = 0.017) proteins to be altered in kidney disease." (PMID 25799079, 2015). "In contrast with C4 levels, C3 levels were lower in the patients with renal disorder." (PMID 26583157, 2015). "One could speculate that the elevated fat content in the OB mice could impair liver function and affect the secretion of MBL, or the reduction could be due to consumption, as suggested, for a reduction in circulating levels of C3 and C4 in patients with renal diseases." (PMID 39000309, 2024). "Also, genetically determined deficiencies of C3 are well known predisposing factors for SLE, but more recently, genetically determined factors leading to modestly low levels of C3 have been proposed as a factor leading to IC in renal disease in SLE." (PMID 35436902, 2022). "However, a limited number of studies have been conducted in order to investigate the renal tubular C3 deposition in subjects with renal diseases, whereas little is known regarding the clinical significance of C3 deposition, notably in pediatric patients with PNS." (PMID 30003098, 2018). "Two genes (C3 and VCAM1) were of particular interest given previous descriptions of their potential use as biomarkers in kidney disease." (PMID 37580326, 2023). "Patients with active kidney disease tended to have lower levels of CH50 and C3 and higher levels of immune complexes detected by C1qBA than those with extra-renal manifestations only." (PMID 33841392, 2021). "In addition to the previously reported cases, decreased AP functional activity and severely decreased serum C3 concentration may be promising biomarkers to identify patients with concomitant AP dysfunction early and may help prevent progression of renal disease." (PMID 25380644, 2014). "The complement drugs are targeting different parts of the complement pathways such as C5 inhibitors eculizumab and ravulizumab, C3 inhibitor (pegcetacoplan APL-2), C1 inhibitors, MASP 1 and MASP2 inhibitors, C5a inhibitors, and Complement Factor D inhibitors for a wide range of kidney diseases." (PMID 38895123, 2024). "Urine S100 proteins A8/A9 and A12 were significantly higher (p<0.05) in patients with SLE with low serum complement C3 and/or C4 and with active renal disease as compared with those without active renal involvement." (PMID 32723832, 2020). "Although our patient underwent examinations for differential diagnosis from other kidney diseases (IgG, IgA, IgM, C3, C4, cryoglobulin, PR3-ANCA, and MPO-ANCA), no clinically significant findings were obtained." (PMID 30646927, 2019). "Our 6-month mouse cohort provides us with what we believe to be the clearest evidence to date that long-term C5 inhibition is unlikely to result in an alternative complement-mediated renal disease, despite the presence of deposited C3 within the glomeruli." (PMID 30714990, 2019).
renal disease (continued). "Although the stage of CKD was not clearly defined in this study, increased C3 mRNA and positive immunostaining for C3 in tubules were observed in patients with FSGS compared with healthy controls, supporting the role of complement activation in the progression of this kidney disease." (PMID 40519169, 2025). "This second group of proteins correlated with renal disease severity but did not display significant correlation with IFN-inducible chemokines, SLE-associated antibodies, and C3, suggesting that this inflammation is temporally distinct to type I IFN and kidney immune complex deposition." (PMID 31594956, 2019). "This could explain why not all patients benefit of an anti-C5 therapy in C3-mediated kidney diseases or during strong complement activation." (PMID 29875766, 2018). "Interestingly, the capacity of patients' IgG to enhance C3 cleavage was not increase in patients with MIg but without kidney disease and the link between an ongoing complement activation in MIg-C3G patients and the MIg remains speculative." (PMID 30333829, 2018). "Furthermore, C3 activation may aggravate existing kidney disease since non-selective filtration of complement proteins may result in intratubular complement activation and tubular damage." (PMID 22282163, 2012).
bacterial infections (61 papers, 2011 to 2025). "Here, we show that C3-deficient A549 cells exhibit reduced cytokine secretion in response to bacterial infection and pathogen-associated molecular patterns (PAMPs), which is restored in cells expressing only cytosolic C3." (PMID 41441980, 2025). "Further investigation revealed reduced cytokine secretion in C3-deficient cells following both bacterial infection and stimulation with various receptor agonists." (PMID 41441980, 2025). "The mutation or deletion of the C3 gene leads to a variety of immune diseases, and increases bacterial infections." (PMID 35281048, 2022). "Here, we evaluated the expression of C3 as it functions in both classical and alternative complement activation pathways, and deficiency of C3 can make humans more susceptible to viral and bacterial infections." (PMID 34358063, 2021). "C3 deficient patients suffer from recurring bacterial infections, but to what extent this corresponds to a pharmacologically induced C3 deficiency remains to be determined." (PMID 34191092, 2021). "C3 deficiency is known to increase the susceptibility of host cells to invasive bacterial infections." (PMID 27367858, 2016). "Patients with point mutations at a 5′ donor splice site in the C3 gene produce dysfunctional C3 protein, and show heightened susceptibility to bacterial infections." (PMID 25188723, 2014). "C3 factor has a critical role in the complement system, and C3 deficiency makes people more susceptible to bacterial infection." (PMID 24369445, 2013). "Despite their promise, long-term systemic C3 inhibition may impair host defense mechanisms, particularly increasing susceptibility to encapsulated bacterial infections such as Streptococcus pneumoniae, Neisseria meningitidis, and Haemophilus influenzae." (PMID 41187099, 2025). "Our findings expand on these results by showing that C3 deficiency disrupts these pathways, leading to a suboptimal immune response that may contribute to increased susceptibility to bacterial infections." (PMID 40008883, 2025). "The complete deficiency of C3, which mediates the opsonization of microbes, typically results in severe encapsulated bacterial infections, especially Streptococcus pneumoniae, Haemophilus influenzae, and Neisseria meningitidis, and immune complex-mediated glomerulonephritis at a young age." (PMID 38406130, 2024). "Moreover, the increase of C3 has been linked to enhanced protection of grey mullet against bacterial infections." (PMID 39563419, 2024). "However, little information is available about the bovine C3 single-nucleotide polymorphisms (SNPs) and their associations with infectious bacterial diseases and complement hemolytic activity." (PMID 35771868, 2022). "Data from humans with homozygous C3 deficiencies highlighted the importance of complement during Hib infections, as human C3 deficiency is associated with recurrent and life-threatening bacterial infections by Hib and other encapsulated bacteria." (PMID 36578495, 2022). "In addition, the glycolysis pathway (ANAGLYCOLYSIS-PWY) had inverse associations with circulating levels of complements C3 and C4, and a positive association with the bacterial infection score generated from whole blood transcriptomic data (all P < 0.05)." (PMID 35045853, 2022). "Thus, the deficiency of C3 leads to severe a bacterial infection, including those caused by meningococci and pneumococci." (PMID 36389821, 2022). "Based on inherited complement defects, patients with transiently low complement may be at similar risk for serious bacterial infection, but the degree of risk related to C3 level and temporal association is unknown." (PMID 32972440, 2020). "Complement C3 deficiency manifests itself into recurrent bacterial infections." (PMID 31159152, 2019). "Persons who have a C3 deficiency are susceptible to bacterial infections." (PMID 28934227, 2017).